NLRP3 (NLR family pyrin domain containing 3)
Diseases named in the same sentence as NLRP3 in open-access papers (continued):
Sharing a sentence is not in itself a finding about the gene and the disease.
influenza (continued). "LAIV (like wild-type influenza) expresses M2 protein in infected cells and therefore activates NLRP3 inflammasomes, resulting in the production of the potent inflammatory cytokines IL-1β and IL-18." (PMID 39591131, 2024). "Recent studies have highlighted that inhibition of NLRP3 inflammasome activation can effectively treat influenza viral pulmonary inflammation." (PMID 37957672, 2023). "It is known that influenza activates the NLRP3 inflammasome during infection and increases influenza-induced disease severity." (PMID 38112660, 2023). "On the opposite side is the research that has shown that the NS1 protein of influenza can inhibit the NLRP3 inflammasome." (PMID 36298668, 2022). "Although outside the scope of this review, it is important to consider that the role of NLRP3 inflammasome activation by influenza is highly debated within the field." (PMID 36298668, 2022). "In the context of influenza infections, the role of the NLRP3 inflammasome and pyroptosis in relation to disease is controversial." (PMID 33499234, 2021). "Of note, ZBP1 is capable of triggering pyroptotic cell death via activating NLRP3 inflammasome, which further aggravate the seriousness of influenza infection." (PMID 34643045, 2021). "The NLRP3 inflammasome and its product interleukin-1β (IL-1β) are pivotal mediators of cellular immune responses to influenza, yet, overactivation of these systems leads to side effects, which hamper clinical applications." (PMID 32714571, 2020). "We are unaware of studies detailing the NLRP3 inflammasome response to influenza infection in either chicken or duck." (PMID 32477965, 2020). "Against other viruses, such as influenza, the NLRP3 activation can be either protective or detrimental depending on the stage of infection and virus load." (PMID 31479495, 2019). "It regulates NLRP3 inflammasome activation and induces the apoptosis, necroptosis, and pyroptosis in the influenza-infected cells." (PMID 31665046, 2019). "Our study showing that the Nlrp3 inflammasome contributes to lethality upon gastrointestinal MNV infection in IFN-unresponsive Stat1-/- mice is in line with this observation in Influenza-infected mice." (PMID 31017981, 2019). "Alveolar macrophages were shown to be the prominent source of IL-1β during influenza infection, and virus triggered the expression of Nod-like receptor protein 3 (NLRP3) inflammasome and pro-IL-1β in these cells." (PMID 29079611, 2018). "In this paper, we demonstrate that IL-1β release during influenza infection is critically dependent on neutrophil-driven activation of the NLRP3 inflammasome in alveolar macrophages and is mediated through the neutrophil antimicrobial peptide mCRAMP." (PMID 29079611, 2018). "Excessive NLRP3 inflammasome activation contributes to aberrant inflammatory responses and causes severe ALI after influenza infection." (PMID 30422993, 2018). "The M2 protein of influenza also acts as a viroporin, promoting viral uncoating within endosomes and stimulating the activation of the NLRP3 inflammasome." (PMID 29552008, 2018). "The activation of the NLRP3 inflammasome during sub-lethal influenza infection plays a critical role in limiting lung damage resulting from infection." (PMID 30013955, 2018). "Influenza has therefore evolved several mechanisms to evade the activation of the NLRP3 inflammasome." (PMID 29552008, 2018). "The use of a specific NLRP3 inhibitor has been noted to significantly protect mice from lethal influenza by reducing the BALF levels of proinflammatory cytokines, such as IL-1β and IL-18, and decreasing the recruitment of inflammatory cells into the lungs." (PMID 30422993, 2018). "In conclusion, our data showing the expression patterns of NLRP3, IL-1β and TNF-α in H9N2 AIV infected mice further support that NLRP3 inflammasome protein play a crucial role in the physiological and pathological processes of influenza infection." (PMID 25547136, 2014).
influenza (continued). "In particular, the reduced levels of IL-1beta and IL-18 are in line with recent reports of impaired NLRP3 inflammasome function in elderly mice during influenza infection." (PMID 24642138, 2014). "This basic data will enhance our understanding of the inflammatory process during influenza and develop the new strategies to anti-influenza based on the NLRP3." (PMID 25547136, 2014). "More recently, RIG-I was reported to induce type I IFN through a MAVS/TRIM25/RNF135 signaling axis following influenza infection, and was shown to have profound effects on NLRP3 inflammasome activation and IL-1β secretion in human lung epithelial cells." (PMID 24273750, 2013). "Three additional reports examined the role of IL-1β, as well as components of the Nlrp3 inflammasome, in control of influenza infection." (PMID 23056330, 2012). "Following murine infection with influenza, aged DC show impairments in NLRP3 inflammasome/caspase-1 activation, and downstream IL-1β and IL-18 production, suggesting age-related impairments in DC pathogen sensing and/or innate activation." (PMID 22862959, 2012). "In particular IL-1β has been shown to be a critical component of host defense against influenza in murine lung infection, induced in response to viral activation of the NLRP3 inflammasome, with influenza stimulating increased IL-1β production by macrophages." (PMID 22031815, 2011). "For example, the roles of the NLRP3 inflammasome and IL-1β in influenza infection remain debated." (PMID 40983621, 2025). "The anti-influenza and anti-inflammatory properties of alkaloids may involve the NLRP3 inflammasome pathway, TLR/NF-κB signaling pathway, and RIG-I pathway." (PMID 40076449, 2025). "Therefore, the immunological responses of the NLRP3 inflammasome pathway must be strictly modulated to avoid hyperinflammatory or immunocompromised states during influenza infection." (PMID 39221016, 2024). "Influenza can also regulate NLRP3 via a second activation phase." (PMID 38249297, 2023). "As we summarized, for example, acetate increases the production of IFN1s with antiviral effects through NLRP3-mediated activation of MAVS located on mitochondria, and, in addition, he restores pathogenic bacterial phagocytosis in macrophages after influenza infection." (PMID 37928517, 2023). "Besides HIV-1, a number of viruses such as influenza or measles have evolved mechanisms to suppress the NLRP3 inflammasome." (PMID 36800238, 2023). "Besides NLRP3, influenza has also been shown to activate RIG-I (which promotes replication) and AIM2." (PMID 36298668, 2022). "In addition, Mfn2 binds to NLRP3 to promote IL-1β secretion after infection with RNA viruses, including influenza, measles, or EMCV." (PMID 35958608, 2022). "However, knockout of NLRP3 or caspase-1 in mice has been shown to increase morbidity and mortality during influenza infection." (PMID 33499234, 2021). "First, alveolar macrophages were significantly more potent than neutrophils at producing IL-1β on a per-cell basis, due to a greater induction of IL-1β and NLRP3 mRNA (and both populations were present in comparable numbers in the airways of influenza-infected mice)." (PMID 29079611, 2018). "Subsequently, we questioned whether a neutrophil-derived product could instead directly activate the NLRP3 inflammasome in the alveolar macrophage during influenza infection." (PMID 29079611, 2018). "Thus, neutrophils are seemingly critical for the provision of the second signal that activates the NLRP3 inflammasome in alveolar macrophages during influenza infection." (PMID 29079611, 2018). "Finally, influenza infection triggers NLRP3 activation, which lead to formation of large multimeric complexes called inflammasomes that cause release of IL-1/IL-18 and pyroptosis." (PMID 30337928, 2018).
influenza (continued). "An abundance of literature has demonstrated that the NLRP3 inflammasome is central to influenza-induced IL-1β production, with alveolar macrophages deemed to be the prominent source of the cytokine, 20 23–25 and we provide several lines of evidence to support this assertion." (PMID 29079611, 2018). "However, NLRP3 inflammasome signaling must be tightly controlled to avoid inducing a hyperinflammatory state after lethal influenza infection." (PMID 30422993, 2018). "In vivo, Nlrp3 inflammasome activation protected mice from influenza infection." (PMID 24273750, 2013). "A recent paper showed that DCs from elderly mice exhibited decreased expression of ASC, NLRP3, and caspase-1 compared with DCs from infected young mice and the concomitant blunted IL-1β response resulted in enhanced morbidity and mortality in influenza-infected elderly mice." (PMID 24409181, 2013). "In addition to the TLRs, RIG-I, NLRP3, and NOD2 have also been implicated in the immune response to influenza; however, the relative contribution of these PRRs to influenza-specific host defense requires additional study." (PMID 21108806, 2010). "Besides, studies provided evidence that pathogens such as human rhinovirus, and influenza may contribute to COPD exacerbation by activating the NLRP3 inflammasome." (PMID 36248872, 2022). "In mice, influenza infection is sensed by toll-like receptor 3 (TLR3), TLR7, retinoid acid-inducible gene I (RIG-I), melanoma differentiation associated protein 5 (MDA-5), and the NOD-like receptor family member NOD-, LRR- and pyrin domain-containing 3 (NLRP3)." (PMID 30337928, 2018). "For instance, during early influenza infection, TLR7/RIG-I signaling and M2 ion channel activity cooperatively promote potassium ion efflux and mtROS generation, activating NLRP3 to enhance IL-1β/IL-18 release." (PMID 40860873, 2025). "MXSGD and SJZD exhibit synergistic effects in the treatment of influenza, as evidenced by the inhibition of TLR7 and NLRP3 inflammatory pathways early in the infection and facilitation of the response later." (PMID 39221016, 2024). "The NLRP3 inflammasome is a multiprotein intracellular complex comprising NLRP3, ASC, and pro-caspase-1 that is activated upon infection with influenza, as well as other RNA viruses." (PMID 36558964, 2022). "It has been proposed that influenza proteins M2 and PB1-F2 can activate NLRP3, alter ion balance, and extensively affect cell homeostasis." (PMID 36298668, 2022). "Both influenza and SARS-CoV viruses induce NLRP3 (NLR family pyrin domain containing 3) inflammasome activation, associated with pyroptosis—a highly inflammatory form of lytic programmed cell death- upon infection with intracellular pathogens." (PMID 34749737, 2021). "It is thought that by regulating the NLRP3 inflammasome, IRF1 contributes to apoptosis and necroptosis during influenza infection." (PMID 32477965, 2020). "A recent report showed in mouse model that Nlrp3 inflammasome activation depends on reactive oxygen species (ROS) and inhibition of ROS induction abolished IL1B production during influenza infection." (PMID 21901105, 2011). "In addition, probenecid and AZ11645373 can target the P2X7 receptor signaling pathway and inhibit the responses of the NLRP3 inflammasome during IAV infection, subsequently limiting excessive inflammation and illness during influenza." (PMID 38249297, 2023). "The ameliorative effect of phillyrin on influenza-induced pulmonary pathological damage may be partly related to the antagonization of CXCR2 and inhibition of NLRP3 inflammasome activation." (PMID 37957672, 2023). "The role of ATP-related NLRP3 activation in influenza infection was demonstrated in cocultures of macrophages and epithelial cells, and it was also shown that ATP signaling through the P2X7 receptor is important for NLRP3 activation in vivo." (PMID 37662905, 2023).
influenza (continued). "Moreover, Z-DNA-binding protein 1 (ZBP1), a novel effector of necroptosis, triggers NLRP3 inflammasome activation and release of IL-1β through the RIPK1-RIPK3-Caspase-8 axis during influenza A virus (IAV) infection." (PMID 36619743, 2022). "In contrast, genes associated with pyroptosis, including CASP4, NLRP3 and GSDMD, were highly expressed in whole lung lysates from macaques with lethal influenza but not from uninfected animals." (PMID 35271686, 2022). "In influenza infection, antibiotic-induced impaired immunity correlates with reduced expression of inflammasome-related genes, including pro-IL-1β, pro-IL-18 and NLR family pyrin domain containing 3 (NLRP3), and impaired CD103+ DCs migration to mLN." (PMID 35880171, 2022). "In the context of influenza infection, the innate immune sensor ZBP1 is emerging as a key regulator of the concurrent induction of NLRP3-dependent pyroptosis, mixed-lineage kinase domain-like pseudokinase (MLKL)-dependent necroptosis, and CASP8-dependent apoptosis." (PMID 32152420, 2020). "In particular, stimulation of macrophages with linezolid (from the oxazolidinone class of antibiotics) or infection of macrophages with influenza and encephalomyocarditis viruses does not require ROS for activation of the NLRP3 inflammasome." (PMID 28729463, 2017). "BBR has been shown to improve lung inflammation in influenza mice by inhibiting NACHT, LRR, and PYD domains-containing protein 3 (NLRP3) inflammasome activation and inhibiting GSDMD-mediated apoptosis by reducing GSDMD expression and suppressing NLRP3 inflammasome-mediated GSDMD activation." (PMID 40076449, 2025). "Multiple inflammasomes can be involved in IL-1β activation, including NLRP3, NLRP1, NLRC4, AIM2, IFI16 and RIG-I, however because GC B cells are not directly infected by influenza infection, we examined NLRP3 and AIM2 as they are activated by stimuli likely to be present in GC B cells." (PMID 40825032, 2025). "In addition, MPL cannot activate the NLRP3 inflammasome in contrast to LPS, and NLRP3 inflammasome plays a critical role in limiting lung damage resulting from influenza infections." (PMID 32428336, 2020). "Most interesting, increased expression of pro-IL-18 with defective NLRP3 activation was observed in dendritic cells from elderly mice during influenza infection, highlighting that IL-18 upregulation may occur in the absence of NLRP3 activation." (PMID 28912710, 2017). "In the absence of expression of M2 protein, the dominant mechanism of inflammasome activation following influenza infection, M2SR is not expected to activate NLRP3 inflammasomes." (PMID 39591131, 2024). "A requirement for ASC, but not NLRP3 or caspase-1, was also demonstrated for antigen-specific humoral immunity after vaccination with MF59-adjuvented influenza." (PMID 32366256, 2020).
Myocardial fibrosis (70 papers, 2016 to 2026). "According to theresults obtained from their study, NLRP3 levels were observed to increase in miceundergoing the procedure, and this situation caused cardiomyocyte hypertrophy,myocardial fibrosis, and cardiac dysfunction." (PMID 37402273, 2023). "The increase in ROS and NLR family pyrin domain-containing 3 (NLRP3) inflammasomes in cardiomyocytes induced by persistent high glucose can also cause inflammation, cardiomyocyte apoptosis, and myocardial fibrosis and exacerbate the development of DCM." (PMID 37479697, 2023). "Most studies have shown that NLRP3 is upregulated in myocardial fibrosis induced by various causes and can promote myocardial fibrosis." (PMID 37249295, 2023). "Knockdown of NLRP3 with siRNA or pharmaceutical inhibition of NLRP3 inflammasome activation reverses myocardial hypertrophy markers and myocardial fibrosis-associated protein expression both in vivo and in vitro." (PMID 36111168, 2022). "Mixed lineage kinase 3 (MLK3) mainly regulates NF-κB/NLRP3 signaling pathway-mediated inflammation and that pyroptosis causes myocardial fibrosis in the early stages of CHF." (PMID 35509275, 2022). "In an AMI mouse model, NLRP3 inflammasomes can activate the formation of IL-1β, cause myocardial damage and myocardial fibrosis, and directly inhibit the formation of NLRP3 inflammasomes." (PMID 33407160, 2021). "Nlrp3 deficiency significantly attenuated cardiac inflammation, myocardial fibrosis and left ventricular dysfunction." (PMID 33628380, 2021). "We found that MLK3 mainly regulates NF-κB/NLRP3 signaling pathway-mediated inflammation and that pyroptosis causes myocardial fibrosis in the early stages of CHF." (PMID 32710001, 2020). "Moreover, GMB and its metabolites have regulatory effects on the NLRP3 inflammasome, and dysbacteriosis will cause activation of the NLRP3 inflammasome, which will further aggravate inflammation or myocardial fibrosis." (PMID 36830978, 2023). "The pathophysiology of SSc-PHI involves both vascular and immune-mediated pathways, exacerbated by the NLRP3 inflammasome and pro-fibrotic cytokines, leading to myocardial fibrosis as the main cardiac manifestation." (PMID 41639006, 2026). "In mice with pressure-overload remodeling, cardiac NLRP3 inflammasome activation enhances greater myocardial fibrosis by the upregulation of TGF-β1 triggered by IL-1β." (PMID 40076547, 2025). "QL down-regulates the TGF-β1/Smad3 signaling pathway through inhibition of the NLRP3 inflammatory vesicle, thereby suppressing myocardial inflammation and myocardial fibrosis." (PMID 40881586, 2025). "IL-1β was identified as a key mediator in promoting the proliferation and differentiation of CFs into myofibroblasts, indicating that NLRP3 inflammasome activation is an important factor mediating the progression of myocardial fibrosis." (PMID 39925805, 2025). "Inositol-requiring enzyme 1α (IRE1α) acted as a sensor of endoplasmic reticulum stress, capable of triggering NLRP3 inflammasome activation, thereby exacerbating the progression of myocardial fibrosis." (PMID 39925805, 2025). "In cardiac fibroblasts, inappropriate activation of NLRP3 inflammatory vesicles can lead to a variety of myocardial dysfunctions including myocardial fibrosis." (PMID 40881586, 2025). "The restoration of CTRP3 expression ameliorated Ang II-induced myocardial fibrosis by inhibiting the P2X7R/NLRP3 inflammasome pathway to reduce α-SMA, collagen I/III, and matrix metallopeptidase (MMP) 2/9 expression." (PMID 39925805, 2025). "Artemisinin pretreatment mitigates MI/R-induced myocardial inflammation, cardiomyocyte apoptosis, and myocardial fibrosis primarily by inhibiting the NLRP3 inflammasome." (PMID 39925805, 2025). "Another study demonstrated that the mechanism by which tretinoin mitigates myocardial fibrosis involves the inhibition of the NLRP3 inflammasome." (PMID 39925805, 2025).